IL1B (interleukin 1 beta)
Diseases named in the same sentence as IL1B in open-access papers (continued):
Sharing a sentence is not in itself a finding about the gene and the disease.
schizophrenia (continued). "Intriguingly, NLRP3/Caspase 1/IL-1β is also involved in the classical pyroptosis pathway, in which IL-1β and IL-18 are activated, and the inflammation is amplified, which may contribute to the pathogenesis of schizophrenia." (PMID 37946206, 2023). "In the future, the relationship between miR-3653-3p and NLRP3, caspase 1, and IL-1β in patients with schizophrenia is worthy of in-depth research and further validating the potential of miR-3653-3p, NLRP3, caspase 1, and IL-1β as a stable biomarker for schizophrenia in diagnostic experiments." (PMID 37946206, 2023). "Furthermore, in the same experimental conditions, we measured the expression levels of the main pro−inflammatory cytokines regulated by NF−kB (i.e., IL6, TNFα, and IL1β), given their proven role in the etiopathogenesis of several psychiatric diseases, including schizophrenia." (PMID 37240042, 2023). "IL-1β may be a marker of the chronic course of schizophrenia or a target for clinical intervention." (PMID 37946206, 2023). "Minocycline adjunctive therapy may be beneficial in schizophrenia, with documented improvement in cognitive, positive, and negative symptoms and reduction of inflammatory cytokines IL-1β and IL-6." (PMID 38259293, 2023). "IL-1β, which can induce the conversion of rat mesencephalic progenitor cells into a dopaminergic phenotype, and IL-6, which decrease the survival of fetal brain serotonergic neurons, both significantly influence the neurotransmitter systems involved in schizophrenia." (PMID 35963926, 2022). "Signs of a peripheral inflammatory response in schizophrenia are indicated by elevated serum/plasma levels of certain pro-inflammatory factors, including prostaglandin E2 and C-reactive protein, as well as some pro-inflammatory cytokines, such as IL-1β, IL-6, IL-8, and tumor necrosis factor-α." (PMID 35722585, 2022). "However, serum levels of IL-1β, corrected for age, gender, body mass index, and smoking have been described as no different in patients with schizophrenia and controls and among subtypes of schizophrenia." (PMID 33746786, 2021). "As for older paternal age, it has been suggested that the observed increased incidence of ASC, schizophrenia and bipolar disorder could be the result of immune dysregulation with increases in pro-inflammatory cytokines IL-1β and IL-6 observed in all three disorders." (PMID 31719968, 2019). "Intraperitoneal administration of interleukin (IL)-1β, IL-6, and IL-2 in mice was shown to stimulate dopamine (DA) utilization in prefrontal cortex, leading to DA deficiency, which is connected with negative symptoms in schizophrenia." (PMID 30178287, 2019). "TNF-α and IL-1β were participated in the processes of neurogenesis or white matter abnormalities, suggesting that altered TNF-α and IL-1β may be associated with negative symptoms of schizophrenia." (PMID 29867314, 2018). "Specifically, the IL1B gene promoter single nucleotide polymorphism (SNP) C-511T (rs16944) has been shown to be associated with schizophrenia in European populations, though the data are not univocal and to affect brain structure and functions in schizophrenic patients." (PMID 29464121, 2017). "Interestingly, some cytokines [IL-12, IFN-γ, TNF-α, soluble IL-2 receptor (sIL-2R)] may be trait markers for schizophrenia, while others are raised during phases of intensified symptoms (IL-1β, IL-6, and TGF-β)." (PMID 24550848, 2014). "Furthermore, previous findings suggested that IL-1β may be involved in the possible link between prenatal exposure to infection and schizophrenia." (PMID 21843369, 2011). "Literature-based analysis suggests that miR-9 exerts predominantly inhibitory effects on schizophrenia-related genes (e.g., IL1B, ABCB1, FGFR1) while promoting the expression of INS, indicating a potential protective role of miR-9 against schizophrenia." (PMID 40779062, 2026).
schizophrenia (continued). "Research indicated that schizophrenia and MDD patients had higher levels of IL-6, TNF-α, and IL-1β as compared to healthy controls." (PMID 40416228, 2025). "High serum levels of interleukin 1β (IL-1β), IL-6, or tumor necrosis factor-α (TNF-α), often manifested during acute relapse of schizophrenia, are significantly reduced by antipsychotic therapy." (PMID 41010622, 2025). "By using the Western blot technique, we found notably high concentrations of the inflammatory mediators IL1β, IL-6, and TNF-α in the serum of patients with schizophrenia compared with in the controls." (PMID 41011185, 2025). "PANSS scores in schizophrenia patients correlated with IL-6 and TNF-α serum levels, whereas MDD patients showed correlations between IL-6 and IL-1β levels and HAM-D scores." (PMID 40416228, 2025). "The PANSS total scores in schizophrenia displayed moderate-to-strong relations with IL-6 and TNF-α (r = 0.54 and r = 0.48), yet IL-6 and IL-1β exhibited these relations with HAM-D in patients with MDD (r = 0.46 and r = 0.41)." (PMID 40416228, 2025). "This study demonstrated that schizophrenia and MDD were inflammatory disorders because enhanced IL-6, TNF-α, and IL-1β levels showed direct links to symptom intensity in affected patients." (PMID 40416228, 2025). "In this study, we discovered that HERV-W env promotes pyroptosis by increasing the expression of NLRP3, CASP1, GSDMD and IL1B, potentially representing a novel mechanism by which HERV-W env influences neuronal cell death in patients with schizophrenia." (PMID 39859234, 2025). "Based on the results of this study, it is suggested that T. gondii-mediated increased IL-1β, TNF-α expression and NF-κB activation in the brain contribute to the pathogenesis of schizophrenia." (PMID 39766497, 2024). "In another study, pathologically higher levels of IL-1β and TNF-α serum, along with NF-κB activation, were found in schizophrenia patients compared to healthy individuals." (PMID 39766497, 2024). "For example, a meta-analysis of cytokines in schizophrenia found higher levels of pro-inflammatory cytokines such as IL-6, TNF-α and sIL-2R in acute patients, and IL-6, IL-1β and sIL-2R in chronic patients than in healthy controls." (PMID 38352871, 2024). "Regarding inflammatory factors, a meta-analysis reported elevated levels of IL-6, IL-1β, and TNF-α in the blood and cerebrospinal fluid of individuals with schizophrenia." (PMID 39324122, 2024). "It is recommended that miRNA levels assess by disease severity and clinical profiles to provide reliable evidence for the concoctions between higher levels of IL-6, IL-1β, TNF-α, and mi-RNAs in patients with schizophrenia in comparison with controls." (PMID 37644489, 2023). "Therefore, IL-1β may be a biomarker for the onset of schizophrenia." (PMID 37270510, 2023). "The serum levels of Interleukin 1 beta (IL-1β), Interleukin 6 (IL-6), and transforming growth factor beta (TGF-β) were found to be elevated in acute phases of schizophrenia." (PMID 37803327, 2023). "IL-1β, IL-2, IL-4, IL-6, BAFF, IFN-α, GM-CSF, NRG1-β1, and GDNF increased but TNF-α and NGF-β decreased in schizophrenia compared to healthy individuals." (PMID 37239308, 2023). "Besides, we found that miR-3653-3p may be associated with negative symptoms of schizophrenia, and IL-1β levels may be positively associated with schizophrenia symptoms, consistent with previous reports." (PMID 37946206, 2023). "In contrast, whole blood stimulation studies in schizophrenia showed elevated concentrations of IL-6, TNF-α, and IL-1β post-TLR2 stimulation, and increased IL-1β alone post-TLR4 and 8 stimulation." (PMID 37627253, 2023). "A meta-analysis showed increased levels of IL-6, IL-8, IL-10, IL-12, IL-1β, IFN-γ, TNF-α, and TGF-β in the blood of patients with schizophrenia, which was similar to our findings." (PMID 35223927, 2022).
schizophrenia (continued). "The first major finding of this study is that IL-23, IL-6, IL-17, and TNF-α were considerably greater in MNP than in SNP, while IL-1β, IL-22, G-CSF, IL-21, IL-17, IL-10, and TNF-α were significantly higher in schizophrenia than in controls." (PMID 36256663, 2022). "Increments in cytokines such as IL-1β, TNF-α, IL-6, and IL-10 have frequently been described in schizophrenia." (PMID 36256663, 2022). "A previous study found evidence for a subgroup of patients with schizophrenia and bipolar disorder positive for the human endogenous retrovirus type W (HERV-W) envelope protein that exhibit increased levels of IL-6 and IL-1β." (PMID 36085284, 2022). "Findings from the current meta-analysis seem to support elevated levels of pro-inflammatory marker cytokines, such as interleukin-6 (IL-6), IL-1β, and tumor necrosis factor A (TNF-A), in the blood and cerebrospinal fluid of patients with schizophrenia." (PMID 33315097, 2021). "Data from 62 studies, analyzed IFN-γ, IL-4, IL-2, soluble IL-2 receptor (sIL-2R), IL-1β, IL-1 receptor antagonist (IL-1RA), TNF-α, IL-6, soluble IL-6 receptor (sIL-6R), and IL-10 in schizophrenia." (PMID 33746786, 2021). "There was a significant increase in the levels of TNFα, IL-1β, and IL-6 and a decrease in the levels of IFN-γ in patients with schizophrenia." (PMID 33552387, 2021). "However, whether or not the activation of IL-1β is causally related to the development of schizophrenia or is a consequence of associated dopaminergic/glutamatergic dysfunction remains to be established." (PMID 33746786, 2021). "Significantly elevated levels of macrophage-derived cytokines IL-1β, IL-6, and TNF-α, as well as the Th1-derived cytokine IFN-γ support the macrophage-T-lymphocyte theory of schizophrenia pathophysiology." (PMID 34199832, 2021). "Proinflammatory cytokines, including interleukin-1β (IL-1β), IL-6, and tumor necrosis factor-α (TNF-α), are thought to contribute to the pathogenesis of psychiatric symptoms in schizophrenia by Kyn pathway activation." (PMID 34393855, 2021). "In a meta-analysis, which included 23 studies (762 participants in total), antipsychotic medication was reported to significantly reduce the plasma levels of IL-1β and interferon γ (IFN-γ) in patients with schizophrenia." (PMID 34955927, 2021). "Schizophrenia patients have been shown to have high levels of inflammatory cytokines, such as TNF-α, IL-1β, and IL-6, as well as high microglial activation throughout the brain as shown by PET scans and postmortem biopsies." (PMID 33854417, 2021). "Other scholars have found that IL-1β gene expression level is positively correlated with PANSS general psychopathological symptoms, and serum IL-1β of patients with schizophrenia is significantly positively correlated with PANSS total score." (PMID 34795793, 2021). "To this end, we focused on a panel of plasma cytokines (IL-1β, IL-6, IL-10, TNF-α, and IFN-γ), which have been used previously to assess signs of peripheral inflammation in major psychiatric disorders such as schizophrenia and animal models of MIA." (PMID 33230204, 2021). "We found marked diagnostic increases in the transcripts of pro-inflammatory cytokines (IL6 and IL1β) and in an acute-phase protein (SERPINA3) in the schizophrenia midbrain." (PMID 31168068, 2021). "Increase in the plasma levels of proinflammatory cytokines, such as IL-1β, IL-6, and TNF-α, have been consistently reported in patients with schizophrenia." (PMID 34393855, 2021). "In the case of IL-1β, IL-6 and TNF-α, their potential roles as trait markers of schizophrenia seem to be supported by correlations with the results of neuroimaging studies,; and in the case of TNF-α and IL-6, also with the experience of early childhood trauma." (PMID 34501305, 2021). "Age of onset negatively correlated with CD14, IL6R, IL1R1, SERPINA3, pan-GFAP and VIM mRNAs in schizophrenia and CD14, IL1B, SERPINA3, pan-GFAP and VIM mRNAs in bipolar disorder." (PMID 34911938, 2021).
schizophrenia (continued). "Depression and schizophrenia patients exhibit dysregulation in their immune function, and IL-1β, IL-2r, IL-6, and TNF-α have been identified as biomarkers of schizophrenia." (PMID 33613171, 2020). "Further, the “high inflammation” schizophrenia subgroup had an even greater increase in ICAM1 mRNA consistent with our own and other experimental results showing that IL-1β up-regulates ICAM1 mRNA in cultured endothelial cells." (PMID 30214039, 2020). "We determined the plasma levels of six cytokines (IL-1β, IL-4, IL-6, IL-10, IL-12 and TNF-α) in schizophrenia patients and healthy controls." (PMID 32038109, 2020). "In the TRC cohort, there were moderately strong, positive, significant correlations between KAT I/II mRNAs and many cytokines assessed (IL-1β, IL-6, and IL-8) and SERPINA3 in schizophrenia and control groups." (PMID 30940904, 2020). "Treatment with typical neuroleptics, haloperidol, and perazine, normalized the release of IL-1β and TNF-α by inhibiting monocyte activity in schizophrenia patients." (PMID 32341334, 2020). "A meta-analysis reported that pro-inflammatory cytokines, including interleukin (IL)-1β, IL-6, and tumor necrosis factor (TNF)-ɑ, were elevated in the peripheral blood of schizophrenia patients." (PMID 32341334, 2020). "In contrast, we detected moderately strong, significant inverse correlations of KMO mRNA levels to IL-1β and SERPINA3 mRNA levels within the PFC of people with schizophrenia." (PMID 30940904, 2020). "Plasma levels of interleukin (IL)-1β, IL-2, IL-6, and interferon (IFN)-γ were elevated in schizophrenia patients compared to those in controls." (PMID 29803226, 2018). "Taken all together, these findings suggest that the increased TNF-α and IL-1β, which may be caused by the activated microglia are related with negative symptoms of schizophrenia and anti-inflammatory may have therapeutic effects on clinical symptoms, especially on negative symptoms in schizophrenia." (PMID 29867314, 2018). "al reported that schizophrenia patients had significantly overexpressed TNF-α and IL-1β in blood mononuclear cells." (PMID 29867314, 2018). "IL-1β, IL-6, and transforming growth factor-β (TGF-β) are schizophrenia state markers, as they increase in acute relapses and first episode psychosis and normalize with antipsychotic treatment." (PMID 29544672, 2018). "The pro-inflammatory cytokines IL-1β, IL-6, and IFN-γ were increased in first-episode schizophrenia compared with controls, similar to previous findings described in meta-analytic studies." (PMID 29803226, 2018). "Future studies will need to determine the relationship between peripheral cytokine levels and expression levels of IL-6, IL-8, and to some extent IL-1β, which have been shown to be elevated in the DLPFC in postmortem tissue from patients with schizophrenia." (PMID 29803226, 2018). "In the case of TLR4 stimulation, there were significantly weaker IL-1β, IL-6, and TNF-α responses in schizophrenia relative to the control subjects (p < 0.01), whereas IL-10 production was intact (p > 0.5)." (PMID 28646138, 2017). "For IL-1β, IL-6 and TNF-α, we observed a significantly higher response in schizophrenia patients than in control subjects (p < 0.05)." (PMID 28646138, 2017). "Meta-analysis including 23 follow-up studies found an increase of sIL-2 and decrease of IL-1β levels and IFN-γ after the treatment with antipsychotics, concluding that antipsychotic drugs show anti-inflammatory effects in schizophrenia." (PMID 28358316, 2017). "The same study suggested IL-1β, IL-6 and TGF-β as schizophrenia state markers, since they were elevated in both the first episode and the relapse of the disease, but these markers were decreased after antipsychotic treatment." (PMID 28358316, 2017). "Both protein and mRNA levels of IL-1β, TNF-α, and microglial markers were significantly increased in postmortem schizophrenia brains in relation to the brains of comparison subjects." (PMID 28396623, 2017).
schizophrenia (continued). "Last, we investigated the mRNA expression levels of MAPK14, GFAP and the inflammation markers, IL1B and IL6 in postmortem brain tissues from schizophrenia patients." (PMID 27801899, 2016). "For individuals with schizophrenia, each inflammatory mRNA in OFC tissue was significantly correlated with its expression in the DLPFC tissue (SERPINA3 r=0.723, P<0.001; IL-1β r=0.744, P<0.001; IL-6 r=0.686, P<0.001; IL-8 r=0.417, P=0.022)." (PMID 27959331, 2016). "Shreds of evidence from preclinical and clinical studies have shown persistent elevation in various inflammatory markers like TNF-α, IL-12, IL-1β, IL-6, IL-1, and interferon (IFN)-γ in first onset and acute relapse schizophrenia subjects who were on antipsychotic medications." (PMID 39907868, 2025). "In the group of patients with early-phase schizophrenia (up to 1 year), positive correlations were found between IL-1β and the intensity of negative symptoms (measured using the PANSS N and SANS scales) after 4-week treatment (r = 0.83 and 0.73, respectively)." (PMID 41010622, 2025). "Both LPS and poly(I:C) treatment induced the expression and activation of NLRP3 and IL-1β in the brain of offspring rats showing schizophrenia-like behaviours In vitro studies show higher baseline and LPS-induced Caspase-1, NLRP3, and secreted IL-1β levels in PBMCs from individuals with ASD." (PMID 40713568, 2025). "Indeed, we used two-step recursive cluster analysis to define a high inflammatory biotype of ~46% of schizophrenia cases based on elevated pro-inflammatory transcripts (SERPINA3, IL6, IL1β, TNFα) in the midbrain across two independent cohorts." (PMID 40335479, 2025). "This indicates that increased IL-1β in our patients was correlated with higher severity of schizophrenia symptoms, both positive and negative." (PMID 40364201, 2025). "Stimulation of whole blood cells from SZ patients with selective TLR agonists results in enhanced release of pro-inflammatory cytokines (including IL-1β, IL-6, IL-8, and TNF-α), further supporting the role of TLRs in regulating neuroinflammation in schizophrenia." (PMID 41346597, 2025). "In the context of schizophrenia, researchers have found evidence of cytokines such as C-reactive protein (CRP), IL-1β, IL-6, IL-12, interferon-γ, and tumor necrosis factor α (TNF-α) being associated with endophenotypes and varying disease status of schizophrenia." (PMID 38445386, 2024). "Follow-up could be continued in the future, or a comparative study could be conducted between the untreated schizophrenia and chronic schizophrenia patients to detect the expression levels of miR-3653-3p, NLRP3, caspase 1, and IL-1β." (PMID 37946206, 2023). "Meta-analytical schizophrenia data have found that the blood and CSF levels of IL-1β, IL-6, and IL-8, but not IL-2, were increased." (PMID 37510730, 2023). "Some research on patients with schizophrenia indicates statistically significantly greater IL-1β, IL-8, IL-17, IL-23, and TNF-α levels in women but not in men, compared with healthy individuals." (PMID 36556337, 2022). "Furthermore, increased levels of IL-1β, IL-6, IL-17, IL-21, IL-22, IL-23, and tumor necrosis factor (TNF)-α were all found to be inversely related to HR-QoL in these schizophrenia patients." (PMID 36011997, 2022). "CCL2, coming from either myeloid cells or astrocytes, can influence the differentiation of tissue macrophages and promotes the production of proinflammatory cytokines including IL-6, IL-1β, and TNF-α which are all elevated in the brains of people with high inflammation schizophrenia." (PMID 35844224, 2022). "We speculated that higher TLR4/NF-κB/IL-1β signaling may compensate for functional deficits of monocytes and, as a result, less increases in monocytic TLR4 levels upon LPS stimulation in schizophrenia." (PMID 36051545, 2022). "Increased IL-22 and IL-6, but not IL-17 or IL-1β, were observed in schizophrenia as compared with healthy subjects." (PMID 36256663, 2022).